MDM2 (MDM2 proto-oncogene)
Diseases named in the same sentence as MDM2 in open-access papers (continued):
Sharing a sentence is not in itself a finding about the gene and the disease.
soft tissue sarcoma (37 papers, 1997 to 2025). A malignant neoplasm arising from muscle tissue, adipose tissue, blood vessels, fibrous tissue, or other supportive tissues excluding the bones. "Increased MDM2 expression can cause downregulation of IGF-1R and in some cancers, such as soft tissue sarcoma, MDM2 expression is associated with a more malignant phenotype." (PMID 24489919, 2014). "differentiated soft tissue sarcomas according to malignancy grade and predicted MDM2-Gene amplification, respectively, achieving AUCs of 0.922 and 0.95, with high sensitivity and specificity values." (PMID 40040725, 2025). "In soft tissue sarcomas, the MDM2 amplification occurs mainly through the so-called double minutes chromosomes (Dmins) mechanism." (PMID 36674856, 2023). "MDM2 is another oncogene shown to be overexpressed in a variety of human tumors, more specifically in soft tissue sarcomas." (PMID 27632538, 2016). "The significance of this finding of MDM2 amplification in 21.9% is uncertain, since up to 40% of other soft tissue sarcomas can harbor amplified MDM2." (PMID 25810689, 2015). "Although MDM2 amplifications were frequently observed in soft tissue sarcoma, the only study examining this in pediatric RMS has shown very low prevalence of MDM2 amplifications (2 out of 20 samples)." (PMID 22550420, 2012). "The human homologue of the murine double-minute 2 (mdm2) gene, HDM2, localized on chromosome 12q13-14, has been reported to be overexpressed in soft tissue sarcomas due to amplification." (PMID 35455947, 2022). "MDM2-ALT1 and MDM2-ALT2 were first described to be expressed in soft tissue sarcoma samples, including liposarcomas, in 2001 by Bartel and colleagues, but without reporting correlation with MDM2 amplification." (PMID 39769278, 2024). "Use case – Soft tissue sarcoma with reported amplification ofKIT,PDGFRA,MDM2,RICTOR andFGF10." (PMID 31608148, 2019). "Recently, the roles of CDK4 have been reported as follows: i) high CDK4 alterations occur in DDLPS among soft tissue sarcomas, ii) CDK4 alteration correlates with worse overall survival, and iii) the levels of CDK4 and MDM2 are not always consistent." (PMID 39588302, 2024).
pancreatic cancer (36 papers, 2012 to 2025). "It is worth noting that the elevated level of MDM2 expression is significantly associated with poor clinical outcome of the patients with pancreatic cancer." (PMID 29558908, 2018). "In advanced pancreatic cancer patients, MDM2 expression is associated with shorter OS and PFS after gemcitabine-based chemotherapy." (PMID 28678832, 2017). "We speculated that HCG11/miR-579-3p/MDM2 axis could be an underlying therapeutic target in the treatment of pancreatic carcinoma." (PMID 34230221, 2021). "In addition, the association between chemotherapy and MDM2 status in pancreatic cancer is largely unknown." (PMID 28678832, 2017). "The results presented here reinforce the potential of hijacking MDM2 as the E3 ligase for the development of novel PROTACs to degrade key overexpressed proteins in pancreatic cancer." (PMID 40317844, 2025). "Continued research and clinical exploration will be essential to fully realize the therapeutic potential of MDM2 inhibitors and to integrate them into the standard of care for metastatic pancreatic cancer." (PMID 39001391, 2024). "While MDM2 amplification is relatively rare in pancreatic cancer compared to other malignancies, its significance as a driver of disease aggressiveness highlights its potential as a therapeutic target." (PMID 39001391, 2024). "Overall, MDM2 amplification represents a promising therapeutic target in the context of metastatic pancreatic cancer management." (PMID 39001391, 2024). "As research progresses, further study of the mechanisms and prevalence of MDM2 amplification in pancreatic cancer, and ongoing clinical trials will provide valuable insights into optimizing the efficacy and safety of MDM2-targeted therapies." (PMID 39001391, 2024). "In recent years, early clinical trials investigating MDM2 inhibitors have reported encouraging results in pancreatic cancer patients." (PMID 39001391, 2024). "In conclusion, the pivotal observations in this study illustrated that HCG11 increased the expression of MDM2 via competitively targeting miR-579-3p to promote the Notch/Hes1 pathway, thereby promoting the progression of pancreatic carcinoma." (PMID 34230221, 2021). "Depletion of HCG11 reduced MDM2 expression at transcription and translation levels in pancreatic carcinoma cells." (PMID 34230221, 2021).
pancreatic cancer (continued). "Next, the qPCR was conducted to analyze MDM2 expression in pancreatic carcinoma samples, indicating that a marked augmentation of MDM2 was presented in pancreatic carcinoma samples when in contrast with the adjacent samples and HPDE6-C7 cells (p<0.01)." (PMID 34230221, 2021). "In contrast to normal cells, MDM2 gene is sometimes amplified and/or aberrantly overexpressed in number of cancers including pancreatic cancer." (PMID 29558908, 2018). "We envision that β-carboline derivatives can be developed as promising dual inhibitors of β-catenin and MDM2 for the treatment of advanced pancreatic cancer." (PMID 29387014, 2018). "The β-catenin and MDM2 oncoproteins are overexpressed and constitutively activated in human pancreatic cancer and contribute to its initiation, progression, and metastasis." (PMID 29387014, 2018). "Consistent with our previous study, MDM2 KD largely reduced SP141’s activity in pancreatic cancer cells." (PMID 29387014, 2018). "As expected, shRNA-mediated knockdown of MDM2 suppressed proliferation rate and tumor growth potential of highly metastatic pancreatic cancer cells." (PMID 29558908, 2018). "The double KD of β-catenin and MDM2 almost completely blocked the inhibitory effects of SP141 on pancreatic cancer cell viability." (PMID 29387014, 2018). "A microarray investigation into a cell model of pancreatic cancer indicated that MDM2 was upregulated along with 39 other metastasis-related genes, including 13 ECM-related genes of which MMP9 was one." (PMID 24236052, 2013). "Additionally, recent progress has shown new possible approaches to treat pancreatic cancer, such as targeting MDM2 amplification, Claudin 18.2, and MTAP deletion." (PMID 39001391, 2024). "Particularly, in de-differentiated liposarcomas, which share similarities with the aggressiveness of pancreatic cancer, MDM2 inhibitors have shown efficacy, hinting at their potential applicability in advancing also the treatment landscape for pancreatic malignancies." (PMID 39001391, 2024). "In addition, USP22 was shown to induce cell cycle protein-dependent kinase inhibitor 1A (CDKN1A) in pancreatic cancer, and MDM2 inhibitors enhanced the anti-pancreatic cancer effect of USP22 overexpression." (PMID 35884607, 2022). "Taken together, our results indicate that ANKHD1 and MDM2 might be novel therapeutic targets in pancreatic cancer." (PMID 34743406, 2022). "Taken together, these findings indicate that ANKHD1 and MDM2 might be a novel therapeutic target in pancreatic cancer." (PMID 34743406, 2022). "Thus, genetic inactivation of E4f1 has been shown to induce autophagy in leukemic cells and MDM2 was also shown to be regulated upon accumulation of the autophagy substrate p62/SQSTM1 in KRASG12D-driven pancreatic cancer cells." (PMID 33406607, 2021). "MDM2 upregulation was observed in numerous human tumors, including pancreatic carcinoma." (PMID 34230221, 2021). "In a word, our study revealed that HCG11/miR-579-3p/MDM2 acted as a ceRNA network to promote the progression of pancreatic carcinoma by activating Notch/Hes1 pathway, further affirming the importance of MDM2/Notch/Hes1 in pancreatic carcinoma." (PMID 34230221, 2021).
pancreatic cancer (continued). "Additionally, previous studies have revealed that MDM2 was identified as one of the primary genes that accelerate the metastasis of pancreatic carcinoma." (PMID 34230221, 2021). "Moreover, the biological function of HCG11/miR-579-3p/MDM2 in pancreatic carcinoma was analyzed by in vitro and in vivo models." (PMID 34230221, 2021). "Therefore, in our study, the expression of HCG11 and its potential target miR-579-3p/MDM2 were analyzed in clinical pancreatic carcinoma and corresponding para-carcinoma tissues." (PMID 34230221, 2021). "Importantly, our PCR results presented that MDM2 expression in pancreatic carcinoma samples was notably increased." (PMID 34230221, 2021). "This study suggests that a double targeting strategy may be a promising approach to improve the efficacy and safety of MDM2 inhibitors for cancer treatment of advanced pancreatic cancer." (PMID 32397368, 2020). "Therefore, therapies inhibiting both β-catenin and MDM2 are suggested to be ideal treatments for patients with advanced pancreatic cancer." (PMID 29387014, 2018). "Herein, dual inhibition of β-catenin and MDM2 may display a synergistic anticancer activity and could be a promising therapeutic strategy for advanced pancreatic cancer." (PMID 29387014, 2018). "In addition, MTS, apoptosis, and cell cycle assays indicated the enhanced effects of USP22 overexpression and MDM2 inhibitor treatment in the inhibition of proliferation, and the induction of apoptosis and cell cycle arrest, in pancreatic cancer cells in vitro." (PMID 34743406, 2022). "Furthermore, the exploration of ANKHD1 inhibitor treatment could provide novel therapy strategies for pancreatic cancer, especially in combination with MDM2 inhibitor treatment, which should be verified by further research." (PMID 34743406, 2022). "Therefore, MDM2 comprises a novel therapeutic target for pancreatic cancer." (PMID 34743406, 2022). "Importantly, the double KD of β-catenin and MDM2 almost entirely blocked SP141’s anti-pancreatic cancer activity, indicating that the dual inhibition of β-catenin and MDM2 by this compound might exhibit a synergistic activity against tumor growth." (PMID 29387014, 2018). "The administration of MA242 (dual inhibitor of MDM2 and NFAT1) in combination with gemcitabine inhibits pancreatic tumor growth and metastasis, providing a promising strategy for the treatment of pancreatic cancer." (PMID 40859234, 2025). "More recently, we have identified a synthetic small molecule NFAT1 and MDM2 inhibitor, termed MA242, which has been shown to inhibit tumor growth in in vitro and in vivo models of pancreatic cancer and HCC." (PMID 32397368, 2020). "Martínez-Bosch and colleagues proved that PARP-1 upregulates MDM2, VEGFR1, and MMP28, accelerating tumor proliferation and angiogenesis in pancreatic cancer." (PMID 26314963, 2015).
pancreatic cancer (continued). "Furthermore, the beta-carboline-derivate SP141, a small molecule inhibitor of MDM2, could induce ubiquitination and degradation of β-catenin in pancreatic cancer cells, which was independent of the effect of the compound on MDM2." (PMID 35327645, 2022).